LINC01266 (long independently transcribed non-coding RNA 1266)
Gene: Long non-coding RNA gene on chromosome 3 (536,062 to 870,015, forward strand). Ensembl gene ENSG00000224957.
Diseases named in the same sentence as LINC01266 in open-access papers:
LINC01266 is named in the same sentence as 1 disease in open-access papers, as found by Europe PMC text mining. Sharing a sentence is not in itself a finding about the gene and the disease.
LINC01266 shares sentences with these, for which no sentence is quoted: Intellectual disability (1 paper).